RNY4P7 (RNY4 pseudogene 7)
Gene: Miscellaneous RNA gene on chromosome 2 (127,798,903 to 127,798,998, reverse strand). Ensembl gene ENSG00000201470.
Homologues: Orthologues: chimpanzee Y_RNA (98% identical), macaque Y_RNA (93% identical). Paralogues in human: RNY4 (93% identical), RNY4P10 (91% identical), RNY4P14 (91% identical), RNY4P24 (91% identical), RNY4P3 (91% identical), RNY4P6 (91% identical), Y_RNA (91% identical), Y_RNA (90% identical), RNY4P17 (89% identical), RNY4P19 (89% identical), RNY4P25 (89% identical), RNY4P37 (89% identical), and 92 more.